IL6 (interleukin 6)
Diseases named in the same sentence as IL6 in open-access papers (continued):
Sharing a sentence is not in itself a finding about the gene and the disease.
colitis (continued). "Both in vitro and in vivo, the colitis increased NF-kB and NF-kB-p65, COX-2, iNOS, IL-1β, IL-6, and TNF-α activity, in addition to decreasing PPARγ expression." (PMID 36677021, 2023). "The balance between pro-inflammatory cytokines, including IL-6, IL-1β, and TNF-α, usually plays a crucial pathological role in colitis by mediating inflammatory responses." (PMID 38138587, 2023). "L. casei LC2W improved symptoms of colitis induced with E. coli O157:H7 by protecting tight junctions and reducing IL-1β, TNF-α and IL-6 in the colon." (PMID 36986118, 2023). "Previous research has revealed that heat-killed L. sakei K040706, which preserve their cell wall components, protect against DSS-induced colitis by suppressing inflammatory mediators such as nitric oxide, TNF-α, IL-1β, and IL-6." (PMID 37317332, 2023). "SCFA has also been reported to ameliorate colitis through suppressing proinflammatory cytokines, such as TNF-α and IL-6." (PMID 36902109, 2023). "Supplementation with B. vulgatus attenuated symptoms of colitis in mice and decreased the expression of TNF-α, IL-1β, and IL-6 in the colon." (PMID 36902001, 2023). "Since more inflammatory cells infiltration and elevated levels of TNF-α, IL-1β, and IL-6 were observed in colonic tissue of DSS-treated mice, we next examined changes of cellular components involved in the colitis with a special focus on macrophages." (PMID 37813835, 2023). "The colitis mice with OX treatment exhibited lower levels of AST, ALT, BUN, CR, MDA and a down-regulated expression of IL-6 and IL-1β, while the activity of SOD was up-regulated." (PMID 38060482, 2023). "As IL-6 drives Th17 generation and is one of the most elevated cytokines in human ICI colitis, results to date suggest an IL-6–Th17 axis contributes to irAEs." (PMID 36622383, 2023). "M10, a novel derivative of Myricetin, prevents ER stress-induced autophagy in inflamed colonic mucosal cells by targeting the NF-κB/IL-6/STAT3 pathway, which develops M10 as a promising regimen in the chemoprevention of colitis and colorectal cancer." (PMID 36593497, 2023). "The main GBE component flavonoids, such as kaempferol and isorhamnetin, have been shown to reduce IL-1β, IL-6, and TNF-α within DSS-induced colitis animal models." (PMID 37111225, 2023). "SM@siRNP can scavenge 2,2-diphenyl-1-picrylhydrazide radical, inhibit NO and proinflammatory cytokine (IL-1β, IL-6, TNF-α), significantly improved the damage of colonic mucosa in DSS-induced colitis mice." (PMID 37033644, 2023). "The results showed that after 7 days of POLP treatment, the concentrations of IL-6 and PGE2 in the colitis group were significantly lower than those in the model group, but only IL-6 and PGE2 decreased." (PMID 37375369, 2023). "The expression of proinflammatory genes, such as IL‐6, TNF‐α and IL‐1β was significantly lower in the colon of KO mice than in WT mice in both acute colitis and tumour samples." (PMID 37341064, 2023). "Milk extracellular vesicles (mEVs) alleviate DSS-induced colitis by reducing TNF-α and IL-6 expression." (PMID 37389342, 2023). "Oral gavage of Rd or CK at doses of 1 mg/kg and 5 mg/kg also suppressed IS-induced colitis: their treatments alleviated colon shortening and down-regulated colonic myeloperoxidase, TNF-α, and IL-6 expression, and NF-κB+CD11c+ cell number." (PMID 36926604, 2023). "Numerous previous studies showed increased expression of inflammatory mediators (such as TNF-α, IL-6 and COX-2) in the brain following TNBS- or dextran sulfate sodium-induced colitis." (PMID 37371401, 2023). "The results showed that CuET significantly attenuated LPS-induced mRNA levels of TNF-α, IL-1β, and IL-6, consistent with its anti-inflammatory effect on the DSS-induced colitis model." (PMID 37284442, 2023). "MC-LR increased the expression of IL-6, IL-1β, TNF-α, and IL-1αin in the DSS-induced colitis model, thereby aggravating the inflammation." (PMID 37505716, 2023).
colitis (continued). "The present study proved PHI reduced the production and release of inflammatory factors such as IL-6, IL-1β, and TNF-α in both LPS-induced RAW264.7 cells and DSS-induced colitis mice." (PMID 36768559, 2023). "The expressions of RFZ1, IL-6, TNF-α, and IL-1β were also increased in CD68+ macrophage detected by IF staining in the colon from mice with colitis." (PMID 37733446, 2023). "AhR activation by FICZ relieved colonic inflammation, reduced IL-6 and claudin-2 expression, and kept intestinal barrier function in a mouse model of DSS-induced colitis." (PMID 36678175, 2023). "Oral administration with apigenin alleviated colon length shortening, decreased levels of colonic myeloperoxidase (MPO), alkaline phosphatase (AKP), TNF-α, IL-6, and restored intestinal microbiome in TNBS and DSS colitis models." (PMID 37298531, 2023). "We recorded remarkable increase in DAI, histopathologic damage, serum TNF-α and IL-6 levels, and MPO activity in mice with DSS-induced colitis." (PMID 37111064, 2023). "L. fermentum improved colitis, reduced TNF- α, IL-1β and IL-6 in serum and induced anti-inflammatory cytokine (IL-10) expression in the colons of DSS-induced colitis mice." (PMID 36986118, 2023). "The levels of TNF-α, IL-6, and IL-1β were increased, and that of IL-10 was decreased after DSS exposure in mice with colitis." (PMID 37047694, 2023). "Increasing evidence has demonstrated that productions of pro-inflammatory cytokines TNF-α, IL-1β and IL-6 are augmented in IBD patients and chemical-induced colitis animal models." (PMID 36830802, 2023). "With a larger degree of fold-induction in treated vs. control animals, our data indicate that IL-6, IL-22 and LT-α would be the most useful markers in a DSS-induced colitis model." (PMID 36672648, 2023). "UC is a repeated colon inflammation characterized by the infiltration of inflammatory cells and expression of NF-kB-dependent pro-inflammatory biomarkers like TNF-α and IL-6." (PMID 37895902, 2023). "Meanwhile, the secretion of proinflammatory factors IL-1β, IL-6, TNF-α, and PGE2 was enhanced, as well as the levels of anti-inflammatory factor IL-10 were reduced in the serum of colitis rats, which was all reversed by EA treatment." (PMID 36910013, 2023). "L. fermentum reduced the signs of colitis and pro-inflammatory cytokines such as TNF-α, IL-6, IFN-γ and IL-12." (PMID 36986118, 2023). "IL-22 mRNA was encapsulated in a novel nanoparticle and fed to a mouse model of acute colitis, and recovery of colonic length and tissue damage was observed, with concomitant reductions in TNF-α, IL-6 and IL-1β expression." (PMID 37389342, 2023). "In conclusion, POLP can exert its anti-inflammatory effect by regulating the IL6/STAT3/COX-2 pathway and can effectively treat colitis." (PMID 37375369, 2023). "Overall, this panel identified IL-6, IL-22, IL-13, LT-α and TNF-α as upregulated inflammatory markers and CD40L as a downregulated marker of DSS-induced experimental acute murine colitis." (PMID 36672648, 2023). "Eudragit RL PO nanoparticles loaded with SM (75 mg/kg/day) can significantly reduce TNF-α, IL-6 and MPO activity in colon tissues, improve macroscopic and histopathological scores of acetic acid-induced colitis mice." (PMID 37033644, 2023). "Mice treated with SCH experienced significant weight gain, effectively alleviating the severity of colitis, and decreasing the levels of inflammatory factors such as TNF-α, IL-1β, IL-18, IL-6, and other related proteins (NLRP3, Caspase-1, SGK1) in UC mice." (PMID 37674245, 2023). "Valeric acid can inhibit the growth of Clostridium difficile and thereby regulate intestinal homeostasis, whereas sodium butyrate can reduce IL-6 and TNF-α levels and thereby improve colitis in mice." (PMID 37065247, 2023). "Consistently, IHC staining also confirmed the downregulated expression of IL-1β, IL-6, TNF-α and COX-2 in colitis model of β6-KO mice." (PMID 37223685, 2023).
colitis (continued). "To determine the mechanism by which neutrophils contribute to colitis, we examined the production of inflammatory factors including TNF-α, IL-1β, and IL-6." (PMID 37813835, 2023). "Oral live ADS024 treatment reduced weight loss, disease activity, colonic mucosal injury, and colonic expression of interleukin 6 (IL-6) and TNFα in dextran sodium sulfate (DSS)-treated mice with colitis." (PMID 38268707, 2023). "It has been shown that feeding colitis rats β-glucans-rich oatmeal reduced the high levels of c-reactive protein (CRP), Interleukin-12 (IL-12), and Interleukin-6 (IL-6) in the walls of the colons after only seven days." (PMID 36769034, 2023). "Next, we measured the expression levels of three selected cytokines, TNF-α, interleukin-6 (IL-6), and CXCL1/KC, in mouse serum to assess the possible anti-inflammatory effects of EVs on the DSS-induced colitis model." (PMID 37966243, 2023). "We verified this theory by ELISA and found that IL-1β, IL-6, and TNF-α in the colon tissue of DSS-induced colitis mice were significantly increased, showing a strong anti-inflammatory process." (PMID 36832972, 2023). "The available clinical data suggest that anti-IL-6 and anti-TNF-α monoclonal antibodies have a certain ameliorative effect on patients with colitis." (PMID 37595257, 2023). "Oral administration of the β-naphthoflavone (an AhR agonist) decreased the severity of colitis and the production of pro-inflammatory cytokines, such as TNF-α, IL-6, and IL-1β in DSS-induced colitis." (PMID 36672703, 2023). "Loading TNF-α with GELNs can downregulate NLRP3, caspase-1, IL-1β, TNF-α, IL-6 and IL-1b, upregulate anti-inflammatory substances such as IL-10 and IL-22 in colon tissue of DSS-induced colitis mice." (PMID 37033644, 2023). "Regarding the DSS-colitis therapeutic design, BLI showed a moderate positive correlation with Il6, while Tgfb1 and the Il10/Il1b1, Il10/Il6, Tgfb1/Il1b1, Tgfb1/Il6, and Tgfb1/Tnfa ratios correlated in the opposite way." (PMID 37047397, 2023). "Terpenoid component bilobalide can inhibit the expression of IL-1β, IL-6, and TNF-α in DSS-mediated colitis." (PMID 37111225, 2023). "Proinflammatory cytokines play a critical role in DSS-induced colitis injury as significant elevation of TNF-α, IL-1β, and IL-6, at both mRNA and protein levels, was observed by QRT-PCR and ELISA." (PMID 37284442, 2023). "L-theanine also weakly decreased the expression of IL-1β, IL-6, and TNF-α, which are neuroinflammation- and colitis-related biomarkers." (PMID 37299451, 2023). "Regarding SAA plasma levels, strong positive correlations with Il6 and Il1b1 stand out both in the TNBS-colitis prevention trial and in the DSS-colitis therapeutic trial." (PMID 37047397, 2023). "In our previous study, the prototype ITA aggravated DSS-induced colitis and increased the levels of pro-inflammatory cytokines TNF-α, IL-1β, and IL-6 secreted by macrophages in vitro." (PMID 36770726, 2023). "Previous studies have demonstrated that the derangement of cytokines drives colitis pathology and disease progression, TNF‐α, IL‐1β, and IL‐6 are important pro‐inflammatory effectors that function in the context of intestinal inflammation." (PMID 37970386, 2023). "In this study, 2′-FL and 3-FL notably alleviated the symptoms of IL-6-induced barrier dysfunction and DSS-induced colitis." (PMID 37111064, 2023). "For organ-specific irAEs, IL-6 levels were higher in patients with thyroiditis and colitis, while IL-22 and SCF levels were higher in patients with colitis." (PMID 36159840, 2022). "MiR-223 is enhancive in experimental colitis stimulated via DSS and mitigates intestinal inflammation via targeting the IL-6/STAT3 pathway." (PMID 35259053, 2022). "The study indicated that, a large number of proinflammatory factors (IFN-γ, IL-1β, IL-6, and TNF-α) were produced in the serum and colonic tissues after colitis was induced by DSS in mice, while the anti-inflammatory factors (IL-10 and IL-4) decreased." (PMID 36159803, 2022).
colitis (continued). "The pro-inflammatory cytokines TNF-α, IL-1β, IL-6, IL-12, and IFN-γ levels in mice with DSS-induced colitis were apparently higher than those of mice in the normal group, but anti-inflammatory cytokine IL-10 was lower (P < 0.05)." (PMID 36171753, 2022). "In the colons of TNBS-induced colitis mice, BS reduced the expression of proinflammatory cytokines TNF-α, IL-1, and IL-6, as well as COX-2 and activation of NF-kB." (PMID 35990343, 2022). "Recently, piperine has been shown to inhibit the levels of colonic NF-κB protein and the mRNA expression of pro-inflammatory mediators (TNF-α, IL-1β, IL-6, iNOS, and COX-2) in rats of TNBS-induced colitis." (PMID 35807865, 2022). "Further, naïve‐HA and HA‐enema treatment reduced serum inflammatory markers (IL‐6, TNF‐α) compared to vehicle in DSS‐induced colitis mice." (PMID 34761543, 2022). "Kaempferol inhibits the NF-κB pathway to reduce IL-6, IL-1β, COX2, NOS, TNF-α, and reduces DSS-induced colitis." (PMID 35566252, 2022). "Previous research reported that an antimurine IL-1ß antibody decreased IL-6 mRNA expression and alleviated pathological symptoms of DSS-induced colitis, suggesting that IL-1β targets itself and IL-6 for progressing colonic inflammation." (PMID 35672695, 2022). "Both IL-22 and IL-6 activate STAT3 signaling, but epithelial STAT3 activation in DSS-induced colitis depends more on IL-22 than on IL-6." (PMID 36142515, 2022). "Overproduction of pro-inflammatory cytokines, such as TNF-α, IL-1β, and IL-6, is the typical feature of the DSS-induced colitis mouse model." (PMID 36033869, 2022). "Polysaccharides isolated from Ganoderma and Lentinula edodes have shown +immunomodulatory activity in colitis animal models through the production of nitric oxide, tumor necrosis factor alpha (TNF-α), and interleukin-6 (IL-6)." (PMID 35576566, 2022). "IL-1 and IL-6 are elevated in patients with IBD, and in murine models involving colonic inflammation, including DSS-induced colonic inflammation." (PMID 35216112, 2022). "CypB expression were positively correlated with expression of IL-6 and TNF-α, suggesting a possible role of CypB in HFD-induced colon inflammation." (PMID 36266267, 2022). "Quantitative analysis showed that the proinflammatory factors secreted by Th1/Th2/Th17, including IL-2, IL-6, TNF-α, IFN-γ and IL-17A significantly increased in the colitis group in both their serum and colonic tissues." (PMID 35372817, 2022). "The pharmacological evaluation showed that FMPs attenuated inflammation in AA-induced colitis by reducing the serum concentrations of TNF-α, IL-6, IL-8, and IL-10 and the colonic concentrations of MPO, MMP9, and CXCR1." (PMID 35620404, 2022). "On the other hand, IRAK3 knockout mice stimulated using colitis-induced model show significantly increased mRNA and protein expression of TNF-α and IL-6 compared to IRAK3 wild type mice." (PMID 35167625, 2022). "EGCG reduced the levels of TNF-α, IL-6, and NF-κB mRNA expression, NF-κB protein, and MPO activity in colon tissue of rats with trinitrobenzene sulfonic acid (TNBS)-induced colitis." (PMID 35807865, 2022). "In line with our findings, the authors showed that IRAK-M plays a key role in downregulating the induction and progression of DSS colitis through the modulation of proinflammatory cytokines such as TNF-α and IL-6." (PMID 35495925, 2022). "The levels of VIP and IL-6 in the colon and brain tissues were also increased in DPP4-/- mice during the acute inflammation phase of colitis." (PMID 35309368, 2022). "The TNBS-induced colitis rats showed significant increases in disease activity scores, serum TNF-α, IL-2, and IL-6 levels, and colonic myeloperoxidase and malonaldehyde content." (PMID 35239781, 2022). "Daidzein is one of the isoflavones that reduces IL6-, IL-8, IL-12, INF-γ, and up-regulates IL-10 in mesenteric lymph node cells in DSS-induced colitis." (PMID 35566252, 2022).
colitis (continued). "The cytokine levels (IL-6, IFN-γ, and TNF-α) in the colitis mouse colon on Day 14 were much higher than those in healthy mice." (PMID 35893896, 2022). "Then, the following were assessed: the colitis activity score, tumor necrosis factor (TNF)-α, interleukin (IL)-2, and IL-6 serum levels, colonic length, and myeloperoxidase, malonaldehyde, and glutathione levels." (PMID 35239781, 2022). "Pretreatment with compounds 7b and 13b alleviated the severity of colitis and concomitantly counteracted the increased levels of RORγt, STAT3, CCR6, IL-6, IL-17, IL-23, TNF-α, and PGE2." (PMID 36077306, 2022). "In colitis models, oral uptake of these particles decreased the pro-inflammatory cytokines (TNF-α, IL-6, and IL-1), raised the anti-inflammatory cytokines (IL-10 and IL-22), and was shown to be a preventive therapy against colitis-related malignancy." (PMID 36298592, 2022). "In some studies involving the use of experimental colitis animal models, peripheral inflammation elevated the levels of proinflammatory cytokines such as TNF-α, IL-1β, and IL-6 in the hippocampus, cerebral cortex, and hypothalamus." (PMID 36275694, 2022). "In addition, to some degree, different levels of Asp administration decreased the gene expression of TLR4 and MYD88 as well as the TNF-α and IL-6 contents in the UC mice, suggesting that Asp could alleviate colitis in mice by regulating the secretion and expression of inflammatory cytokines." (PMID 36145082, 2022). "The mass accumulation of IL-6, IL-1β and TNF-α is one of the features of DSS-induced colitis, which amplifies the inflammatory cascades and accelerates the disease progression." (PMID 35211182, 2022). "Transcript levels of IL-6, IL-1β, and TNF-α were considerably higher in both colitis groups in this investigation." (PMID 35054518, 2022). "Corylin significantly reduced Ifnγ, Tnf-α, Il-6, Il-1β, Nlrp3, Asc, Pannexin, and Pro-caspase 1 mRNA expression and protein levels in DSS-induced colitis mice." (PMID 35269806, 2022). "It has been shown that RA inhibits the induction of iNOS and COX-2 expression and production of pro-inflammatory cytokines such as IL-6, IL-22 and IL-1β in DSS (dextran sulphate sodium)-induced colitis in the mouse model." (PMID 35079027, 2022). "We confirmed the expression of IL-6 and ADAMDEC1 in plasma samples from colitis, ileocolitis, ileitis, polyarteritis nodosa (Pan), ulcerative colitis (left-sided), idiopathic gastroparesis (IG) and diabetic gastroparesis (DG) by ELISA." (PMID 35563399, 2022). "These T-cell responses can result in effector cytokine production that contributes to the high levels of TNF and IL-6 produced by innate cells in both forms (acute and chronic) of DSS colitis." (PMID 35705557, 2022). "We tested expression of interleukin-6 (IL-6), a well-established indicator of inflammation, in blood and colonic tissue using ELISA and found that IL-6 was increased in DSS-induced colitis mice and decreased after switching back to normal water (Rec 7D)." (PMID 35563399, 2022). "We also discovered that DSS activated the signaling pathway NF-κB and increased IL-1β, IL-6, and TNF-α in DSS-induced colitis mice." (PMID 36033869, 2022). "M2 macrophage-derived exosomes upregulated Treg cells and IL-4, reduced the production of the proinflammatory cytokines IL-1β, IL-6 and IL-17A, reduced the severity of DSS-induced colitis in mice, and played a protective role in colitis." (PMID 36045437, 2022). "The effects of AOS on proinflammatory cytokines were further investigated by ELISA analysis of IL-1β, IL-6, TNF-α, IFN-γ, and IL-10 levels in the serum of DSS-induced colitis mice." (PMID 35889822, 2022). "EV were shown to suppress induced p65 translocation in a mice colitis model, effectively reducing the release of proinflammatory cytokines TNF-α, IL-6, and IL-17A, and attenuating clinical symptoms of colitis." (PMID 35335634, 2022).